LINC01305 (long independently transcribed non-coding RNA 1305)
Gene: Long non-coding RNA gene on chromosome 2 (174,326,027 to 174,341,598, forward strand). Ensembl gene ENSG00000231453.
Diseases named in the same sentence as LINC01305 in open-access papers:
LINC01305 is named in the same sentence as 5 diseases in open-access papers, as found by Europe PMC text mining. Sharing a sentence is not in itself a finding about the gene and the disease. The quoted sentences say what the papers report.
esophageal squamous cell carcinoma (3 papers, 2022 to 2025). Esophageal squamous cell carcinoma (ESCC) is a type of esophageal carcinoma (EC) that can affect any part of the esophagus, but is usually located in the upper or middle third. "Previous research has shown that BNC1 serves as a key transcriptional activator in esophageal squamous cell carcinoma and that LINC01305 recruits BNC1 to act on G-protein pathway suppressor 1 to promote tumor progression." (PMID 40444282, 2025). "LINC01305 has been shown to regulate the target gene HTR3A mRNA through interaction with IGF2BP2 and IGF2BP3, thereby participating in the metastasis and proliferation of esophageal squamous cell carcinoma." (PMID 36204323, 2022). "Moreover, linc01305 increases the stability of HTR3A mRNA by interacting with IGF2BP2, thereby promoting the metastasis and proliferation of esophageal squamous cell carcinoma." (PMID 35299748, 2022).
cervical cancer (2 papers, 2021 to 2022). A primary or metastatic malignant neoplasm involving the cervix. "In addition, LINC01305 regulated the epithelial-mesenchymal transition (EMT) in cervical cancer and lung cancer through different pathways." (PMID 36384476, 2022).
tumor (4 papers, 2021 to 2025). "Moreover, exosomes with forced expression of LINC01305 was associated with the promotion of tumor growth in xenograft mice." (PMID 33638945, 2021). "During the in vivo experiments, we observed that the tumor volume of xenograft mice injected subcutaneously with LINC01305-overexpressing C-33A cells had larger tumor tissues, whereas the silencing of LINC01305 inhibited tumor growth." (PMID 33638945, 2021). "Furthermore, the pro-tumor role of LINC01305 was also observed in xenograft mice by promoting tumor growth." (PMID 33638945, 2021). "Additionally, the upregulation of LINC01305 promoted tumor growth in xenograft mice." (PMID 33638945, 2021). "By immunostaining Ki67, a proliferation marker of tumor tissues, we observed that the expression level of LINC01305 was higher in xenograft tissues with a higher level of Ki67, while xenograft tissues with low expression of Ki67 detected a lower expression of LINC01305." (PMID 33638945, 2021).
cancer (1 paper, 2022). A tumor composed of atypical neoplastic, often pleomorphic cells that invade other tissues. "In oesophageal squamous carcinoma, LINC01305 was found to regulate HTR3A mRNA, thereby promoting cancer cell metastasis and proliferation." (PMID 36384476, 2022).
LINC01305 also shares sentences with these, for which no sentence is quoted: lung carcinoma (1 paper).